CDC20 (cell division cycle 20)
Diseases named in the same sentence as CDC20 in open-access papers (continued):
Sharing a sentence is not in itself a finding about the gene and the disease.
breast cancer (continued). "ER-positive or PR-positive breast cancer patients tended to express lower CDC20 gene compared with ER-negative or PR-negative patients." (PMID 32285914, 2020). "Cdc20 was shown as a prognostic candidate for breast cancer because of its elevated Cdc20 mRNA expression level and its correlation with increased tumor size in cancer patients." (PMID 32882786, 2020). "The present study was performed to analyze the expression pattern, potential function, and distinct prognostic effect of CDC20 in breast cancer using several online databases including Oncomine, bc-GenExMiner, PrognoScan, and UCSC Xena." (PMID 32285914, 2020). "Later, it was verified by qRT-PCR analysis that CDK1, PLK1, and CDC20 were the direct targets of podophyllotoxin in breast cancer cells." (PMID 32848800, 2020). "CDC20 was expressed higher in breast cancer tissues than normal tissues from patients in our hospital, consistent with the results from databases." (PMID 32285914, 2020). "In the present study, we performed a bioinformatics analysis of the clinical parameters and survival data related to CDC20 in breast cancer patients by pooling and analyzing several online tools." (PMID 32285914, 2020). "We further investigated the prognostic value of CDC20 in breast cancer using the PrognoScan database." (PMID 32285914, 2020). "Consistently, using UALCAN website, we also found that higher mRNA CDC20 was expressed in breast cancer tissues than in normal tissues (P<0.05)." (PMID 32285914, 2020). "To verify the results from databases, we compared the mRNA CDC20 expression in breast cancer tissues and adjacent normal tissues of patients by real-time PCR." (PMID 32285914, 2020). "High level of CDC20 was found to be related to aggressive course of breast cancer and poor patient outcome, after 20 years follow-up of 445 patients." (PMID 32043523, 2020). "The comparison among five subtypes of breast cancer further reveals the subtype-dependent expression pattern of Cdc20." (PMID 31669221, 2019). "In breast cancer, CDC20 was reported to bind and promote proteasomal degradation of SMAR1, thus promoting migration and invasion capabilities of cancer cells." (PMID 31106147, 2019). "The basal-like breast cancer, the most aggressive and metastatic subtype, exhibits the highest average expression level of Cdc20 (10.75), while the luminal A subtype has the lowest average expression level (8.20)." (PMID 31669221, 2019). "For instance, severe accumulation of Cdc20 was detected in breast cancer cells and colon cancer cells compared to normal epithelial cells and adjacent normal tissues in cancer patient specimens." (PMID 31669221, 2019). "According to the test set (GSE25055) and validation set (GSE426568), three hub genes (ASPM, CDC20, and TTK) were significantly associated with the prognosis of breast cancer patients." (PMID 31106147, 2019). "To characterize the effect of Cdc20 PROTACs, we have systematically measured the dose-dependent Cdc20 degradation stimulated by each of the 15 designed Cdc20 PROTACs in various breast cancer cells, including MCF7 and MDA-MB-231 cells." (PMID 31669221, 2019). "Induced degradation of Cdc20 by CP5V leads to significant inhibition of breast cancer cell proliferation and resensitization of Taxol-resistant cell lines." (PMID 31669221, 2019). "In both cultured-cell and preclinical breast cancer models, we demonstrated that the degradation of Cdc20 by CP5V induces mitotic inhibition that, in turn, suppresses cancer cell proliferation." (PMID 31669221, 2019). "Overexpression of cell division cycle 20 (CDC20) is associated with poor prognosis of prostate cancer, breast cancer, and colon cancer." (PMID 31737652, 2019). "Using CP5V, we have carefully conducted validation experiments and investigated the dose-dependent effect and time course for Cdc20 degradation as well as Cdc20 ubiquitination in various breast cancer cell lines." (PMID 31669221, 2019).
breast cancer (continued). "Results from our TCGA and pathological analyses demonstrated the abnormal elevation of Cdc20 in breast cancer tissue, especially in triple negative breast cancer." (PMID 31669221, 2019). "Among them, ASPM, CDC20, and TTK were negatively associated with relapse-free survival (RFS) of breast cancer patients using Kaplan Meier survival curves by log-rank test." (PMID 31106147, 2019). "Immunohistochemistry analysis further described elevated Cdc20 and securin as the hallmark of a triple-negative breast cancer (TNBC) with a short survival time window for breast cancer patients." (PMID 31669221, 2019). "CDC20 is frequently seen over-expressed in several cancers such as breast cancer, cervical cancer, glioblastomas, ovarian cancer and others." (PMID 30563222, 2018). "It has been reported that Cdc20 is over-expressed in breast cancer cells compared to normal mammary epithelial cells." (PMID 29020948, 2017). "Collectively results demonstrated that Cdc20 limits the expression of SMAR1 at the proteasomal levels in different breast cancer cell lines." (PMID 28617439, 2017). "In the case of breast cancer, we have found three exclusive pathways, including Cdc20: phospho-APC/C mediated degradation of cyclin A, regulation of beta-cell development and biological oxidations." (PMID 29020948, 2017). "We found that Cdc20 functions as an oncogene by limiting the tumor suppressive activity of SMAR1 in higher grades of breast cancer, at least in part." (PMID 28617439, 2017). "We observed that SMAR1 and Cdc20 shared reciprocal levels of expression in higher grades of breast cancer cell lines and patient samples." (PMID 28617439, 2017). "Mounting evidence has implied that CDC20 exerts oncogenic function in human tumorigenesis including pancreatic cancer, breast cancer, colorectal cancer, and lung cancer." (PMID 27623074, 2017). "NAHA, a N-alkylated amino acid-derived sulfonamide hydroxamate, inhibited the expression of Cdc20 in breast cancer cells." (PMID 27626499, 2016). "Ganodermanontriol (GDNT), a ganoderma alcohol from medicinal mushroom, inactivated Cdc20 in breast cancer cells." (PMID 27626499, 2016). "Nevertheless, a DsiRNA against CDC20 was the most potent RNAi reagent in our hands, and it also effectively slowed the growth of breast cancer xenografts in an animal model." (PMID 25763370, 2015). "The overexpression of BUB1 or CDC20 induces misregulation of APC, and is associated with the chromosomal instability and poor outcomes in breast cancer patients." (PMID 24758163, 2014). "Among the larger modules, we identified one associated with the cell-cycle (CDC2, CDC20, MYBL2, MAD2L1) consistent with many other studies showing the importance of cell-cycle genes in breast cancer prognosis." (PMID 20673354, 2010). "Additionally, CDC20 plays a crucial role in breast cancer progression, with high expression levels in a variety of breast cancer cell lines and HG primary breast carcinoma tissues." (PMID 39795587, 2024). "Similarly, an independent study demonstrated elevated CDC20 expression in breast cancer patients by analyzing 445 cases with 20 years of follow-up data." (PMID 39795587, 2024). "Time-course inhibition experiments coupled to Western blot analysis confirmed that interfering with APC/C activation by Cdc20 in breast cancer cells treated with APN and Cbz-APN impaired the proteolytic degradation of the genuine APC/C substrates Cyclin B and Cdc20." (PMID 39595615, 2024). "Down-regulates Cdc20 in breast cancer cells and induces apoptosis." (PMID 37682144, 2023). "In addition to PLK1, PGCCs up-regulated CDC20 and CCNB1, which are associated with aneuploidy/polyploidy, adverse clinical outcomes of breast cancer patients, and resistance to adjuvant therapy." (PMID 38129519, 2023). "To study whether CDC20 accumulation is involved in the mechanism of drug resistance developed by breast cancer cells, we analyzed CDC20 knockdown or overexpression in two TNBC cell lines, MDA-MB-231 and MDA-MB-468." (PMID 35954396, 2022).
breast cancer (continued). "Additionally, a strong correlation between CDC20 and hnRNPU expression in breast cancer patients was shown by using correlationAnalyzerR." (PMID 35954396, 2022). "Furthermore, higher expression levels of CDC20 were observed in TNBC compared with other breast cancer subtypes." (PMID 35954396, 2022). "CP5V-induced degradation of Cdc20 may be an effective treatment strategy for breast cancer anti-mitotic therapy." (PMID 35680848, 2022). "In addition, the expression of CDC20 was significantly and positively correlated with the increase of clinical stages in multiple cancer types, including adrenal cancer, breast cancer, kidney cancer, and lung cancer." (PMID 34527589, 2021). "Remarkably, previous studies have revealed that the upregulated expressions of CDK1 and CCNB1 are correlated with the worse OS in the basal subtype breast cancer, while CDC20, CCNB1, and CDK1 could act as diagnostic and prognostic markers in breast cancer." (PMID 34646403, 2021). "Our results showed that the expression levels of the CDC20 gene were significantly elevated in prostate cancer, kidney cancer, bladder cancer, breast cancer, colon cancer, esophageal cancer, gastric cancer, head and neck cancer, lung cancer, liver cancer, uterine cancer, and pancreatic cancer." (PMID 34527589, 2021). "Moreover, the patients with a more advanced stage of breast cancer tended to express higher level CDC20." (PMID 32285914, 2020). "To verify the results above, we further compared the mRNA CDC20 expression in breast cancer tissues and adjacent normal tissues of patients in our hospital and found that CDC20 was expressed higher in breast cancer tissues, consistent with the results from databases (P<0.05)." (PMID 32285914, 2020). "High Cdc20 and securin immune expression are associated with extremely poor outcomes in breast cancer patients, and overexpression of RPL17 affects breast cancer-associated brain metastases (Yuan, Wang & Cheng, 2018)." (PMID 32461838, 2020). "CDC20 could be considered as a potential predictive indicator for prognosis of breast cancer with co-expressed TPX2 gene." (PMID 32285914, 2020). "Moreover, we used 22 pairs of breast tissues from breast cancer patients in our hospital to compare the expression of CDC20 gene between the cancer tissues and normal tissues by real-time PCR." (PMID 32285914, 2020). "However, the significance of CDC20 expression in the development and prognosis of breast cancer remains largely unclear." (PMID 32285914, 2020). "Conversely, Scarff–Bloom–Richardson (SBR) grade, Nottingham prognostic index (NPI), epidermal growth factor receptor-2 (HER-2) status, basal-like status, and triple-negative status were positively related to CDC20 expression in breast cancer patients with respect to normal individuals." (PMID 32285914, 2020). "CDC20 over-expression means short-term breast cancer survival." (PMID 32833968, 2020). "In the present study, we performed a deep bioinformatics analysis of the clinical parameters and survival data related to CDC20 in breast cancer patients using several online databases in order to evaluate the prognostic significance of CDC20 gene in breast cancer treatment." (PMID 32285914, 2020). "Moreover, we also found patients with a more advanced stage of breast cancer tended to express higher levels CDC20." (PMID 32285914, 2020). "Moreover, the inhibition of Cdc20 prevented the migration of breast cancer cell lines and consistently, the overexpression of Cdc20 accelerated the metastatic ability of cancer cells in in vitro conditions." (PMID 32882786, 2020). "We anticipate that CP5V-mediated Cdc20 degradation could potentially provide an alternative solution to target the oncogene Cdc20 and address the Cdc20-dependent resistance to taxanes in breast cancers." (PMID 31669221, 2019).
breast cancer (continued). "As further confirmation of the importance of Cdc20 in breast cancer, we performed immunohistochemical analyses of Cdc20 with human breast specimens and observed severe Cdc20 protein accumulation in luminal A/B, Her2 and TNBC tissues in comparison with the adjacent normal tissues." (PMID 31669221, 2019). "Interestingly, a majority of Survivin interacting molecules that were found to be significantly regulated by Pirfenidone are also associated with the mitotic spindle (MAD2L1, BUB1, BUB1B, BUB3, CDC20) and were shown to be increased in human breast cancer." (PMID 32039023, 2019). "Enhanced expression of CDC20 is more often found in various tumor types (including lung adenocarcinoma, breast cancer, bladder cancer and prostate cancer) and might serve as a novel cluster of prognostic biomarkers." (PMID 31289358, 2019). "In addition, BG+/-TMZ significantly decreased p-CDC2, p-AURKB, p-TOP2A, p-KIF20A and p-CDC20 expression in breast cancer cells." (PMID 30038716, 2018). "We then evaluated whether Cdc20 regulates SMAR1 levels in higher grades of breast cancer cell lines." (PMID 28617439, 2017). "Cdc20 and securin overexpression predicted short-team breast cancer survival." (PMID 28165402, 2017). "Moreover, genistein controlled Cdc20 expression, leading to regulation of cell cycle in breast cancer cells." (PMID 27626499, 2016). "As CDC20 is oncogenic in a number of human cancers, including breast cancer, cervical cancer, and gastric cancers, CDC20 may regulate TICs in other cancers." (PMID 25938542, 2015). "Therefore, NAHA suppresses growth of breast cancer cells through the down-regulation of expression of CDC20." (PMID 22479587, 2012). "Moreover, Cdc20-mediated proteasomal degradation of SMAR1 has been studied in breast cancer cells." (PMID 33863392, 2021). "Therefore, the close interaction of TACC3 with CKAP5, AURKA, and CDC20 may suggest the role of TACC3 in the progression of breast cancer, although future mechanistic studies are needed to verify this possibility." (PMID 34149795, 2021). "We characterized the effect of CP5V in destroying Cdc20, arresting mitosis, and inhibiting tumor progression by measuring protein degradation, 3D structure dynamics, cell cycle control, tumor cell killing and tumor inhibition using human breast cancer xenograft mouse model." (PMID 31669221, 2019). "Genistein, a phytoestrogenic isoflavonoid, has been found to partially exert its tumour‐suppressive effect by inhibiting the expression of CDC20 in GBM, hepatocellular carcinoma and breast cancer cells." (PMID 40439120, 2025). "We identified several DEGs involved in the cell cycle, including CDK1, CHEK1, CDC25C, BUB1, CDC20, and TTK, which not only are related to breast cancer patient survival but also have existing targeted drugs." (PMID 38166892, 2024). "Overexpression of CDC20 and CCNB1 has been identified in tumor tissues from breast cancer, glioblastoma, ovarian cancer, and ductal adenocarcinoma." (PMID 39795587, 2024). "The protein expression levels of CDC20 in TNBC are also significantly higher than in Luminal and HER2+ subtypes of breast cancer." (PMID 35954396, 2022). "A PROTAC designed to target the CDC20-APC/c complex and inhibit mitotic progression of breast cancer cells in vitro was reported in 2019." (PMID 36293188, 2022). "PKMYT1, MYBL2, and CDC20 participate in GO terms of the most upregulated KEGG processes and are involved in the development of breast cancer." (PMID 34834441, 2021). "CDC20, TOP2A, RRM2, and UBE2C were highly expressed not only in HCC, but also in breast cancer and other tumors." (PMID 34568357, 2021). "Through the comprehensive analysis of the databases, we found that the expression of CDC20, CDK1, and PLK1 are increased in breast cancer." (PMID 32848800, 2020). "As a result, there were nearly 2.1% (CDC20, CDK1), 1.2% (RRM2), 0.9% (BUB1B), 0.8% (CCNA2), 0.7% (CCNB2) of breast cancer samples included in cBioPortal had genetic changes." (PMID 33083112, 2020).
breast cancer (continued). "Recently, the CDC20 and BIRC5 small interfering RNAs delivered by additive polyplexes displayed novel therapy efficacy in breast cancer cell." (PMID 32043523, 2020). "In the current study, we obtained 283 overlapping DEGs and six hub genes (RRM2, CDC20, CCNB2, BUB1B, CDK1, and CCNA2) related to the occurrence and development of breast cancer via comprehensive bioinformatics analysis." (PMID 33083112, 2020). "Dysregulated Cdc20/APC/C have been reported in a variety of cancers, including gastric, lung, cervical, endometrial, liver, ovarian and breast cancers." (PMID 31669221, 2019). "More convincingly, the result of qRT-PCR using breast cancer tissues and matched paracancerous tissues exhibited a significant upregulation of ASPM, CDC20, and TTK in breast cancer compared to paracancerous tissues (P < 0.001)." (PMID 31106147, 2019). "To test how the abundance of Cdc20 would change after removing CP5V from the medium, we treated the breast cancer cells with CP5V and then removed CP5V followed replacement with fresh medium." (PMID 31669221, 2019). "In this study we evaluate the potential MGMT’s role in control of therapeutic, clinically relevant, cell cycle regulators involved in breast cancer oncogenesis (CDC2, TOP2A, AURKB, CDC20, KIF20A, Cyclin A2, Cyclin B2, Cyclin D1)." (PMID 30038716, 2018). "We show that O6-benzylguanine (BG), an MGMT inhibitor decreases CDC2, CDC20, TOP2A, AURKB, KIF20A, cyclin B2, A2, D1, ERα and survivin and induces c-PARP and p21 and sensitizes ER positive breast cancer to temozolomide (TMZ)." (PMID 30038716, 2018). "We next investigated the invasiveness of breast cancer cells expressing either SMAR1-WT or SMAR1-D1 in the absence and presence of ectopic expression of Cdc20." (PMID 28617439, 2017). "Our results (based on PCR analysis and inhibition of cell growth) highlighted three specific mediators, namely CDC20, RAD51, and CHEK1, as therapeutic targets in breast cancer cells." (PMID 25763370, 2015). "The mRNA and protein levels of CDC20 and BUB1 have been shown to be significantly higher in breast cancer cell lines and in high-grade primary breast cancer tissues." (PMID 25385471, 2015). "In addition, we also found that SETDB2 knockdown diminished the interaction between CDC20 and BUBR1 or APC3 (APC/C complex component protein) in MCF7 breast cancer cells." (PMID 38151757, 2024). "We did not see a significant difference in hnRNPU levels in breast cancer cells with CDC20 overexpression or knockdown." (PMID 35954396, 2022). "Moreover, we compared the expression profiles of CDC20 with a series of genome stability-, chromosome segregation-, mitotic exit-, and CDC20-APC/C pathway-related genes between different breast cancer subtypes and normal tissues." (PMID 35954396, 2022). "The elevated expression of CDC20 is often observed in cancer, including NSCLC and breast cancer." (PMID 34307447, 2021). "Nevertheless, whether these drugs could exert therapeutic effects on breast cancer by inhibiting the over-expression of RRM2, CDK1 and CCNA2, or whether CCNB2, BUB1B and CDC20 are promising therapeutic targets still need to be supported by further research." (PMID 33083112, 2020). "There were negative expression correlations of hsa-let-7a-5p-CCNB2, hsa-let-7c-5p-CCNB2, hsa-let-7a-5p-AURKB, hsa-miR-30a-5p-CDC20, hsa-miR-30a-5p-MYBL2, hsa-miR-29c-3p-OIP5, hsa-miR-10b-5p-CHAF1B, hsa-miR-195-5p-CCNE1, and hsa-miR-497-5p-CCNE1 in ERα positive breast cancer." (PMID 32500028, 2020). "Recently, CDC20 has been demonstrated to act as an oncogene in breast cancer progression, However, studies on role of CDC20 in breast cancer are seldom reported till now, most of which are not systematic and conclusive." (PMID 32285914, 2020). "Moreover, after analyzing breast cancer patient data in the TCGA database using the UCSC Xena web-based tool, again we confirmed a positive correlation between CDC20 and TPX2 expression, as shown in the heat map." (PMID 32285914, 2020).